CD4 (CD4 molecule)
Diseases named in the same sentence as CD4 in open-access papers (continued):
Sharing a sentence is not in itself a finding about the gene and the disease.
tumor (continued). "In addition to enhanced anti-tumor effects by CD8+ T cells, provision of tumor-reactivity to CD4+ T cells by high-affinity TCR may enhance the efficiency of in vivo tumor destruction by cooperative functions of CD8+ and CD4+ T cells." (PMID 30626427, 2019). "Interestingly, combination of anti-PD-1 with BayK8644 was associated with an increased absolute number and percentage of TCRβ+ CD4+ RORγt+ T cells in TDLN and increased frequency of tumor-specific CD8+ T cells within the tumor microenvironment compared with anti-PD-1 monotherapy." (PMID 31085177, 2019). "Finally, we found that the densities of CD3 + and CD8 + cells were higher in MSI-H tumours than in MSS tumours, but that the densities of CD4 + and FOXP3 + cells were not affected by the MSI status of the tumour." (PMID 31488881, 2019). "Furthermore, we observed a reduced CD4+/CD8+ ratio of tumor infiltrating lymphocytes in the absence of PDPN+ myeloid cells." (PMID 30972297, 2019). "The activation of an effective anti-tumor immune response requires cancer antigens to be taken up and processed by antigen-presenting cells (APCs) which in turn present antigen-derived peptides to CD8+ and CD4+ T cells in complex with HLA class I and II molecules, respectively." (PMID 31888734, 2019). "B cells, which are important players in the cross-talk of the innate and adaptive immunity, recovered at V5 and increased during nivolumab treatment, concomitant with the number of CD3+/CD8+, CD3+/CD4+, and CD3+/CD56+ T cells that might also contribute to protective anti-tumor immunity." (PMID 30747241, 2019). "Therefore, changes in the number, distribution, or functional status of CD4+ T, CD8+ T, or total (CD3+) T cells may affect tumor outcomes." (PMID 30632318, 2019). "Notably, TRAPs-elicited CD4+ T cells inhibited CD4+ and CD8+ effector T cell function in an IL-6- and IL-10-dependent manner and induced IL-10-producing regulatory B cells (Bregs) via IL-6, IL-10 and IL-21, thereby promoting tumor growth and metastasis." (PMID 31300052, 2019). "Both CD4+ T-cell lines did not respond to HLA-unmatched tumor cell lines, suggesting that our defined PD-L1241-265 peptide could efficiently stimulate PD-L1-expressing tumor-reactive HTLs." (PMID 31221178, 2019). "Moreover, we differentially analyzed CD4+ and CD8+ T cells, as the two main T-cell subsets differentially recognize antigens via HLA-class II or class I molecules, and exert definite effector functions in the immunological tumor control." (PMID 31275310, 2019). "Interestingly, differential production of the pro-inflammatory cytokine, IL-17 by CD4− and CD4+ liver iNKT cells has been reported, which could explain the superior anti-tumor response of the CD4− subset." (PMID 31569599, 2019). "Also, we found fewer naïve CD4+ T cells, CD4+ naïve/memory ratio, and CD8+ naïve/memory ratio in responders than non-responders and an unfavorable predictive value of naive CD4+ T and CD4+ naïve/memory ratio for tumor response after SBRT." (PMID 31080362, 2019). "Neither gemcitabine treatment nor tumor resection significantly influenced alveolar macrophages, dendritic cells (DCs), NK cells, B cells, CD4+ T cells, or CD8+ T cells in the lungs, which is consistent with previous reports that gemcitabine preferentially targets certain myeloid cell populations." (PMID 31488209, 2019). "Transient CD4 depletion from the circulation but not continuous CD4 depletion from the tumor might be sufficient to exert antitumor T-cell responses due to IT1208 monotherapy." (PMID 31340866, 2019). "To test this hypothesis, we depleted NK cells, CD8+ T cells, and CD4+ T cells by administering mAb PK136 (anti-NK1.1), 2.43 (anti-CD8a), and GK1.5 (anti-CD4) intraperitoneally every 3 days, respectively, before the mice were inoculated with tumor cells." (PMID 31849942, 2019). "Surprisingly, we observed fewer tumor-infiltrating CD4+ T cells in mice lacking CD8+ T cells." (PMID 31112530, 2019).
tumor (continued). "When compared with other cells of the tumor immune infiltrate, also in an acidic microenvironment, TAMs seem to be more efficient at incorporating pHLIP Var3-AF546 because a greater number of cells showed a higher amount of inserted peptide when compared with CD4+ or CD8+ T cells and DCs." (PMID 31710308, 2019). "The antitumor immune response was amplified by photodynamic therapy (PDT), where it effectively eradicated the tumor and distant metastasis in B16-F10 melanoma model by promoting cytokine secretion (TNF-α and IFN-γ) and the frequency of the tumor infiltrating lymphocytes (CD8+ and CD4+)." (PMID 31754376, 2019). "Because autologous tumor mononuclear cells (TMCs) were not available for this patient, we tested the reactivity against tumor ascites mononuclear cells (AMCs) and found that CD4+ T-cells produced IFN-γ when co-cultured with the AMCs but not with the autologous PBMCs." (PMID 31221207, 2019). "However, in the no-NAC cohort, the test of prognostic interaction between tumor infiltrating CD4 T cell score and gC1qR expression showed that there was a significant interaction between these two factors for overall survival (p = 0.002)." (PMID 31681580, 2019). "CD4+ T cells can induce potent anti-tumor immune responses in various ways, either indirectly by helping other immune cells, such as tumor-specific CTL and DCs, within the tumor microenvironment or directly by targeting tumor cells through cytolytic mechanisms." (PMID 30813491, 2019). "Constitutive STAT3 activation in tumor-residing DCs reduces expression of MHC class II and costimulatory molecules, impairs the antigen-presenting function of DC and contributes to the expansion of tumor-infiltrating FOXP3+ T-cells and attenuates CD4+ Th cell responses." (PMID 31480382, 2019). "Therefore, CD4 T cells do not directly target cancer cells but promote the cross-priming of CD8 T cells to tumor antigens by CD40 ligand-mediated DC activation." (PMID 31221199, 2019). "To investigate the relationship between neoantigen load and TILs, we used gene expression data in tumor tissues to measure the abundance of relative cell compositions of each immune cell type, including B cell naïve, B cell memory, T cell CD8 and T cells CD4 memory-activated in TILs." (PMID 31533728, 2019). "Furthermore, CD40 expression on tumor cells correlated with a longer overall survival (OS), suggesting that the interaction between tumor cells and CD40L+ CD4+ T cells could stimulate antigen presentation and lymphoma-specific T-cell responses." (PMID 31261914, 2019). "Our expansion protocol starts with depleting CD4+ and CD8+ T cells followed by polyclonal expansion of the remaining T cells with anti-CD3 antibody, which results in DNTs with a mixture of different subsets of γδ- as well as αβ-DNTs that are highly cytotoxic to tumor cells." (PMID 30670085, 2019). "Moreover, CD4+CD25+Foxp3+ Treg cells were quantified in tumors and showed significant increase in AAV-pCD4-shDNMT1-injected tumor but significant decrease in AAV-pCD4-DNMT1-injected tumor." (PMID 31006654, 2019). "Furthermore, depletion of CD4+ and CD8+ T cells significantly reversed the effect of cetuximab+IL-1α-NP suggesting that IL-1α in combination with cetuximab can induce a T cell-dependent anti-tumor immune response." (PMID 30890189, 2019). "In TC, the extent of tumor-infiltrating CD4+ cells does not appear to predict patient outcome." (PMID 31412566, 2019). "Help from tumour-specific CD4+ cells is often necessary for DC activation and upregulation of co-stimulatory ligands, as innate immune receptors on DCs are often not sufficiently activated by tumour material." (PMID 30232514, 2019). "g. the expression of inhibitory receptors such as PD-1, the immunosuppressive tumor microenvironment, the lack of sufficient CD4+ T-cell help or the action of suppressive cytokines, regulatory T cells or myeloid derived suppressor cells have been suggested to contribute." (PMID 31497249, 2019).
tumor (continued). "Systemic treatment of sildenafil, a phosphodiesterase-5 inhibitor, resulted in decreased levels of VEGF, MDSCs, and Tregs as well as increased tumor infiltration of CD4+ T cells, but not CD8+ T cells, which also increased the survival of only tumor-bearing female mice." (PMID 31652904, 2019). "Initially, we identified both monocytes (CD14+) and pDC as cell populations which expressed significantly more ICAM-1 than NK cells, CD4+ and CD8+ T cells, therefore, we hypothesized that these two cell types may act as key regulators of CVA21-mediated anti-tumor immunity." (PMID 31262361, 2019). "In addition, the frequency of CD4+ FOXP3+ Tregs, the proportion of ST2+ CD4+ FOXP3+ Tregs, and IL-33 protein expression in the colon all positively correlated with tumor scores (i.e. the sum of the relative size of all tumors in a given mouse), irrespective of the genetic background." (PMID 31165767, 2019). "However, in some cases this mechanism eliminates a T-cell subset with a necessary function (e.g., CD4+ helper T cells in CD4 CAR T cells), which may reduce the anti-tumor activity of these CAR T cells." (PMID 30891427, 2019). "Moreover, akin to depleting DC, targeting IL-27 and iNOS were tumor protective in PDA and abrogated many elements of the characteristic CD4+ T-cell Tr1-like surface phenotype and cytokine profile in the TME, although mechanistic links to specific DCs subsest remains to be defined in vivo." (PMID 30926808, 2019). "As determined by flow cytometry, α-PD-1 monotherapy did not significantly affect tumor infiltration of total CD4+ or CD8+ T cells but, unexpectedly, it consistently and significantly skewed the balance between CD4 + CD25 + Foxp3+ Tregs and CD4 + Foxp3- Th cells." (PMID 30832732, 2019). "Moreover, (R)-crizotinib alone or with CDDP induced PD-1 expression on tumor-infiltrating CD4+ Foxp3− but not in CD4+Foxp3+ (Treg) cells bearing the exhaustion marker ICOS." (PMID 30940805, 2019). "At the same time, IgA-positive B cells could be involved in antigen presentation, skewing CD4+ T cells towards functional phenotypes that are negative or suboptimal for anti-tumor response." (PMID 31665076, 2019). "A possible explanation could be immune heterogeneity in the tumor as the HE and CD4, CD8, CD20 IF stainings were not performed on serial sections." (PMID 31784511, 2019). "Treatment with the survivin peptide cocktail vaccine was also found to reshape the tumor microenvironment by increasing the tumor infiltration of both CD4+ and CD8+ T cells but not Treg cells, therefore tipping the balance toward a highly efficient immune response." (PMID 31439015, 2019). "Interestingly, the authors reported that BKM120 does not alter the number of CD8+ T-cells inside the tumor, but an increase of CD4+ T-cells migrating on the neoplastic lesion was observed, with production of IFN-Υ." (PMID 31500143, 2019). "Moreover, the hyaluronan synthesis in CAFs modulated by ESCC cells was capable of promoting adhesion of CD4+ but not CD8+ T cells to xenografted tumor tissues, affecting the tumor immune response." (PMID 31771653, 2019). "However, as a monotherapy, VGSC blockers may yield only short-term success since depleted CD4+ T-cells would ultimately reduce immunological memory and compromise CTL tumor re-challenge." (PMID 30191140, 2018). "Similarly, number of CD8+ T cells but not CD4+ T cells in the LLC tumor formed in Pld2−/− mice was decreased." (PMID 29674728, 2018). "Additionally, a correlation between increased tumor-infiltration by IFN-γ producing CD4 and CD8 T cells, and the increased frequency of Th17 cells in the tumor tissue could be detected." (PMID 29032503, 2018). "Indeed, Wieckowski and colleagues demonstrated that tumor-derived exosomes, but not DC-derived exosomes, induced a substantial expansion of the CD4+CD25+FOXP3+ Treg population." (PMID 29696022, 2018).
tumor (continued). "Flow cytometry analysis of tumor-infiltrating cells freshly isolated from syngeneic tumors revealed no changes in the proportions of CD4+, CD8+ T cells, Treg cells, NK cells, B cells, monocytes, dendritic cells or myeloid-derived suppressor cells (myeloid or granulocytic) upon CC1 treatment." (PMID 30349641, 2018). "However, our experimental design does not allow us to assess the role of CD4 T cells in CD8 T cell mediated anti-tumor responses." (PMID 30499773, 2018). "Nonetheless, in the DEN-induced HCC model, CD8+ T cells produced IFNγ and TNF-α, but not IL-17; CD4+ T cells, however, were a potential source of IL-17 and could be acting as a subset with pro-tumor function (unpublished)." (PMID 30150983, 2018). "Interestingly, a positive CD4+/CD8+ ratio with (33%) or without (37%) positive PD-L1 expression in tumor cells was more frequently observed in patients ≥ 75 years." (PMID 30216999, 2018). "Although CD8 T cells are important for the elimination of cancer cells by cytotoxicity, CD4 T cells are also required for efficacious anti-tumor immunity, through direct effector function, helper activity for CD8 T cells, and enhancement of effector cell infiltration at the tumor site." (PMID 29508006, 2018). "Although CD8+ T-cells in the tumor were activated and expanded to a greater or lesser extent by these therapies, tumor growth suppression was achieved only by anti-PD-1, anti-PD-1/4-1BB combined, or by anti-CD4 treatment, but not by anti-CTLA-4 or anti-4-1BB monotherapy." (PMID 29348598, 2018). "IL-2 may be provided by host CD4 T cells activated by homeostatic proliferation in tumor-bearing non-lethally irradiated mice." (PMID 30546366, 2018). "Finally, treatment of ovarian carcinoma with attenuated strain of the parasite T. gondii (CPS) led to an increase in CD4+ and CD8+ T cell infiltration into the tumor microenvironment, activation of tumor-resident T cells, and enhanced IFN-γ production by T cell populations." (PMID 29765907, 2018). "Also in the CD4+ T cells, expression of CXCL13 appeared to be biased to the tumor fraction." (PMID 30505306, 2018). "Similarly, IL-22 mRNA expression was also decreased in response to GSI treatment in CD4+ T cells from nontumor and tumor sites (P<0.0001)." (PMID 30473538, 2018). "Moreover, the presence of CXCR4 expressing CD4+CD45RA+ T cells correlated with absence of primary tumor ulceration." (PMID 30420855, 2018). "The absence of a potent direct anti-tumor activity of IL-12/15/18 pre-activated NK cells in these mouse studies might be due to the lack of host CD4 T cells and insufficient IL-2 that may be instrumental in maintaining durable anti-tumor responses." (PMID 30546366, 2018). "However, these CD4 T cells were not able to suppress outgrowth of liver tumors without significant amounts of tumor-specific CD8 T cells." (PMID 29032503, 2018). "TILs such as CD4+ and CD8+ T cells, B lymphocytes, Natural Killer (NK)-T cells, as well as innate immune cells such as NK cells, macrophages and DCs, are then recruited in order to eliminate nascent neoplastic cells, acting as an extrinsic tumor suppression mechanism." (PMID 30042343, 2018). "Besides, an absence of gut microbiota shows a significant increase in anti-tumor mature T cells [Th1 (IFN gamma+CD4+CD3+) and Tc1 cells (IFN gamma+CD8+CD3+)] in the tumor microenvironment with an unknown mechanism." (PMID 30567565, 2018). "Notably, anti-PD1 treatment did not significantly alter CD4+ T cell infiltration in either tumor (MOC22 p= 0.2015, MOC2 p=0.1104)." (PMID 29423108, 2018). "It is noteworthy that tumor inhibition was dependent on CD4+, but not CD8+, T cells." (PMID 30135425, 2018). "We found that the tumor-associated CD8+ T cells from the TgMGLL mice expressed notably higher level of IFNγ than the WT mice, indicating a dominate role of TgMGLL on CD8+ T cells, but not on CD4+ T cells." (PMID 29968710, 2018).
tumor (continued). "Very similar results were also observed in GR9-B7 tumor-bearing mice, with a significant decrease (p < 0.05) in TCD3+ (42.3 vs. 51.9%), mainly TCD4+ (35.1 vs. 40.6%), and TCD8+ (7.2 vs. 9.7%) lymphocytes, and a significant increase in Treg (5.8 vs. 2.9% of CD4+)." (PMID 29434605, 2018). "Overall, the maturation of DCs by PSPEI-PAA nanocomplex has activated the CD3+CD8+ cytotoxic T cells for the tumor killing and due to unknown reasons the CD3+CD4+FOXP3+ Treg cell population were affected by the PSPEI-PAA nanocomplex administration in the B16F10 tumor mice." (PMID 30960988, 2018). "Very similar results were also observed in GR9-B7 tumor-bearing mice, with a significant decrease (p < 0.05) in TCD3+ (25.3 vs. 33.1%), mainly TCD4+ (19.7 vs. 26.1%), and TCD8+ (5.7 vs. 6.9%) lymphocytes, and a significant increase in Treg cells (6.9 vs. 4.4% of CD4 +)." (PMID 29434605, 2018). "The most complex forms of immunoediting are the adaptive responses mediated by CD4 and CD8 tumour-specific T lymphocytes driven by tumour neo-antigens, resulting in either tumour elimination, equilibrium between immune surveillance and tumour growth, or tumour escape from immune responses." (PMID 29950452, 2018). "Our results would argue that such therapy may not be accompanied by negative effects on CD4 T cell functions which are necessary for anti-microbial protection and in some cases for anti-tumor effects as well." (PMID 29352298, 2018). "It is crucial for protection against viral, intracellular bacterial infections and tumor control, that the innate recognition of pathogens leads to the production of IFN-γ by NK and/or natural killer T (NKT) cells, which in turn influences the generation of IFN-γ-producing CD4+ and CD8+ T cells." (PMID 30037030, 2018). "The immunologic aspect of the anti-tumor effects induced by DHAs in combination with IC blocking therapy was demonstrated by the highest degree of CD3 infiltrating T cells, including both CD8+ and CD4+ T cells, detected in tumors from mice treated with the combination regimen." (PMID 30581389, 2018). "In murine models, whole brain radiotherapy resulted in upregulation of MHC Class I and increased infiltration of CD8+ and CD4+ T-cells into the tumor microenvironment, although murine models do not allow recapitalization of fractionated radiation therapy in humans." (PMID 30740109, 2018). "Loaded tumour proteins are the basis of tumour immunotherapy, and different antigen loading methods will affect the major histocompatibility complex type I and type II antigen presentation pathways, respectively, which triggers CD8+ and CD4+ T lymphocyte activation." (PMID 29680844, 2018). "Likewise, samples with scores of 0–2 for PD1, CD4, and CD8 were encoded as “none or mild,” whereas scores of 3–4 were encoded as “dense” lymphocytic infiltration in the tumor microenvironment." (PMID 30144808, 2018). "The interplay of CD4 and CD8 T cell responses may also counteract tolerance induction by the tumor and lower the threshold of tumor immune recognition for CD8 T cell epitopes by induction of epitope spreading to antigens that do not trigger tumor remission without CD4 help." (PMID 29032503, 2018). "Interestingly, IL-22 production and IL-22/AhR mRNA was significantly elevated in lung-resident CD4+ T cells from tumor site in comparison with those from nontumor site (all P<0.0001)." (PMID 30473538, 2018). "Could it be possible that contrary to accepted dogmas, CD4+ T cells may be able to lyse tumor cells themselves without reliance on CD8+ T cells?" (PMID 30140266, 2018). "Indeed, the tumour immunity that was observed was reliant upon the CD4 T-cells, but independent of CD8 T-cells." (PMID 29570634, 2018).